CDH5 (cadherin 5)
Diseases named in the same sentence as CDH5 in open-access papers (continued):
Sharing a sentence is not in itself a finding about the gene and the disease.
neuroblastoma (4 papers, 2012 to 2025). Neuroblastoma (NB) is the most common solid, extracranial childhood tumor. "In neuroblastoma (NB) cells, genistein treatment led to demethylation of the CDH5 promoter and decreased the expression of DNMT3B." (PMID 41226811, 2025). "Moreover, CDH5 is a candidate tumor suppressor and low expression strongly correlated to decreased survival in neuroblastoma." (PMID 25325012, 2014). "Moreover, CDH5 is a candidate tumour suppressor and low expression strongly correlated to worse survival in neuroblastomas." (PMID 22905093, 2012).
non-small cell lung carcinoma (4 papers, 2016 to 2025). A group of at least three distinct histological types of lung cancer, including non-small cell squamous cell carcinoma, adenocarcinoma, and large cell carcinoma. "A previous study had reported a downregulation of CDH5 in Bulgarian patients with early-stage non-small cell lung cancer." (PMID 27028764, 2016).
schizophrenia (4 papers, 2019 to 2022). A major psychotic disorder characterized by abnormalities in the perception or expression of reality. "Tight junction proteins such as CDH5 and OCLN that contribute to BBB integrity were found to be elevated in relation to inflammation in postmortem tissue in schizophrenia." (PMID 30214039, 2020).
vascular tumor (4 papers, 2014 to 2024). "In this study, we generated a murine model of mutant GNAQ-driven vascular tumors by conditionally expressing GNAQQ209L in Cdh5 (or Pdgfb) expressing ECs." (PMID 37024491, 2023).
bladder cancer (3 papers, 2022 to 2024). "According to our qRT-PCR result, the expression of CDH5 in T24 cells was the lowest among the 7 bladder cancer cell lines." (PMID 37809080, 2023). "Further experimental verification indicated that CDH5 was low-expressed in bladder cancer (BCa) and this was positively correlated with a better prognosis of BCa patients." (PMID 37809080, 2023). "We further confirmed the expression of CDH5 in bladder cancer (BCa) tissues and cell lines." (PMID 37809080, 2023). "In the Manhattan plot of male bladder cancer cases, there were peaks satisfying a suggestive level of p < 10−5 between LINC00922 and CDH5 in chromosome 16, and between LINC00473 and PDE10A in chromosome 6, but they were outside the genetic regions in the regional plots of GWAS results." (PMID 35328002, 2022).
cardiac hypertrophy (3 papers, 2020 to 2024). "Under HFpEF, the protective effects of lovastatin on diastolic functions, cardiac hypertrophy and fibrosis, and exercise capacity were observed in tamoxifen-injected CDH5-Cre-ERT2 mice, but not in tamoxifen-injected AP-2αflox/flox/CDH5-Cre-ERT2 mice." (PMID 38580662, 2024).
fibrosis (3 papers, 2020 to 2023). the formation of excess fibrous connective tissue in an organ or tissue in a reparative or reactive process. "In vivo, cardiac ischemic injury, cardiac fibrosis, and even occlusion formation were also observed in Cdh5-KO mice." (PMID 36700213, 2022).
Insulin resistance (3 papers, 2020 to 2021). Increased resistance towards insulin, that is, diminished effectiveness of insulin in reducing blood glucose levels. "BMPER eKO mice, similarly to its global depletion, displayed hyperinsulinemia, glucose intolerance, and insulin resistance without weight difference compared to their littermate control (eWT, BMPERflox/flox; Cdh5-CreER−/−) mice." (PMID 33772019, 2021).
lymph node metastasis (3 papers, 2016 to 2023). "In NSCLC tissues, the expression of CDH5 has been reported to be associated with lymph node metastasis and poor prognosis." (PMID 27362942, 2016). "Also, the expression levels and/or roles of miR-142, miR-33b, RAD51B, REV3L, and CDH5 in cervical cancer lymph node metastasis need further clarification." (PMID 32457603, 2020).
lymphoma (3 papers, 2019 to 2024). A malignant (clonal) proliferation of B- lymphocytes or T- lymphocytes which involves the lymph nodes, bone marrow and/or extranodal sites.
Right ventricular hypertrophy (3 papers, 2022 to 2026). In this case the right ventricle is more muscular than normal, causing a characteristic boot-shaped (coeur-en-sabot) appearance as seen on anterior- posterior chest x-rays. "We confirmed a significant increase in RVSP and right ventricular hypertrophy in PAH compared with Control mice for both the Cdh5-CreERT2-TdTomato and C57BL/6 lines and a significant increase in the proportion of fully remodelled vessels in PAH C57BL/6 mice." (PMID 34528097, 2022). "To examine the effects of Cre gene, we also treated tamoxifen-induced Cdh5(PAC)-CreERT2 control mice with hypoxia and examined the effects on accumulation of αSMA-positive cells to distal PAs, right ventricular hypertrophy, and RVSP." (PMID 36203755, 2022). "Hypoxia stimulated accumulation of αSMA-positive cells to distal PAs and increased Fulton's index and RVSP in Cdh5(PAC)-CreERT2 mice, suggesting that inhibition of αSMA-positive cell accumulation, right ventricular hypertrophy, and RVSP in p16iΔEC mice is not because of the effects of Cre gene." (PMID 36203755, 2022).
acute lymphoblastic leukemia (2 papers, 2017 to 2019). Leukemia with an acute onset, characterized by the presence of lymphoblasts in the bone marrow and the peripheral blood. "In other childhood cancers, VE-cadherin is overexpressed in Ewing ́s sarcoma and is a stem cell marker of Philadelphia positive (Ph+) cells, including Ph+ acute lymphoblastic leukemia (ALL) and chronic myeloid leukemia blast crisis cells, where CDH5 contributes to cell survival." (PMID 31324051, 2019).
amyloid (2 papers, 2023 to 2026). "Consistent with our data, a study in APP/PS1 mice - a mouse model for studying amyloid pathology - indicated a disruption in CDH5 expression that occurred before plaque formation and BBB breakdown." (PMID 41566484, 2026).
anemia (2 papers, 2019 to 2022). A reduction in the number of red blood cells, the amount of hemoglobin, and/or the volume of packed red blood cells. "There were no changes in erythrocyte hemoglobin protein, erythrocyte size, or erythrocyte volume upon Cdh5-Cre–driven deletion; this is in contrast to the decreased erythrocyte volume and anemia in Hba1 global knockout animals (Hba1–/–)." (PMID 36302779, 2022). "Analyses of these fetuses showed that, as was the case in conventional ESAM-null mice, severe anemia occurred in approximately half of Cdh5-BAC-CreERT2·ESAMflox/flox fetuses." (PMID 31813828, 2019).
Arthritis (2 papers, 2017 to 2024). Inflammation of a joint. "This was associated with >2-fold elevation in levels of the endothelial marker Cdh5 mRNA, suggesting increased angiogenesis in joints of Hsd11b1MKO mice following arthritis." (PMID 28676523, 2017).
Ataxia (2 papers, 2023). Ataxia refers to impaired coordination of voluntary muscle movement. "Twelve days after the initiation of tamoxifen administration, we noted that one of TRAF7fl/-·Cdh5(PAC)-CreERT2 (Traf7iECko = inducible endothelial cell knockout) mice developed a pronounced ataxia with seizure-like behavior." (PMID 37583551, 2023). "Given that the Cdh5-driven Cre-line has been well-characterized for its endothelial expression, we initially hypothesized that the ataxia phenotype was a consequence of pathological oxidative stress on the vasculature." (PMID 37248315, 2023).
bladder tumors (2 papers, 2013 to 2024). "Kdr and Cdh5 were also downregulated in mouse MB49-I tumours following decorin knockdown, thus suggesting involvement of DCN in regulation of angiogenesis during human bladder tumour progression." (PMID 24142880, 2013).
cavernomas (2 papers, 2019 to 2020). "To further prove that Ccm3−/− cells can form cavernomas and recruit surrounding Ccm3+/+ cells, we isolated endothelial cells from acute P7 Cdh5(PAC)-Cre-ERT2/Ccm3f/f/R26R-Confetti mice and we injected these cells into the brains of adult wild-type mice." (PMID 31235698, 2019). "Finally, the endothelial cells lining the cavernomas overexpressed EndMT markers if compared to the cells of surrounding normal vessels, thus resembling the pathogenesis already shown by the Cdh5(PAC)-Cre-ERT2/Ccm3f/f model." (PMID 31235698, 2019). "In the chronic model of the Cdh5(PAC)-Cre-ERT2/Ccm3f/f/R26R-Confetti mice, not all the endothelial cells lining the large cavernomas were Confetti positive; i.e. Ccm3−/−." (PMID 31235698, 2019).
cervical cancer (2 papers, 2020 to 2024). A primary or metastatic malignant neoplasm involving the cervix. "Among them, two miRNAs (miR-502 and miR-33b) and two key genes (PTPRC and CDH5) were first reported to be potential novel biomarkers for cervical cancer." (PMID 32457603, 2020). "We showed that four miRNAs (miR-502, miR-145, miR-142, and miR-33b) are independent and common prognostic biomarkers for patients with cervical cancer, and seven proteins (CXCL12, IGF1, PTPRC CDH5, RAD51B, REV3L, and WDHD1) are key genes significantly related to lymph node metastasis." (PMID 32457603, 2020).
endometrial cancer (2 papers, 2024 to 2025). Primary or metastatic malignant neoplasm involving the endometrium (mucous membrane that lines the endometrial cavity). "Taken together, these findings suggest that STAT3 can directly activate CDH5 transcription by binding to its promoter region in endometrial carcinoma and that IL-10 can further promote transcription." (PMID 38459564, 2024). "The mRNA level of CDH5 was significantly correlated with JAK1 and STAT3 levels in endometrial cancer." (PMID 38459564, 2024).
epilepsy (2 papers, 2022 to 2023). A brain disorder characterized by episodes of abnormally increased neuronal discharge resulting in transient episodes of sensory or motor neurological dysfunction, or psychic dysfunction. "In epileptic Cdh5‐CreERT2;CDK5f/f mice, although the total protein level of CaMKII had no change and no neurons were lost, autophosphorylated CaMKII decreased, which may play an important role in memory deficits caused by epilepsy." (PMID 35770064, 2022). "Recently, our previous studies have shown that brain endothelial CDK5 deletion induces progressive reactive astrogliosis and results in the development of spontaneous epilepsy in Cdh5‐CreERT2;CDK5f/f mice." (PMID 35770064, 2022). "Moreover, to clarify the effects of AEDs on the mRNA levels of epilepsy‐related and synapse‐related proteins in Cdh5‐CreERT2;CDK5f/f mice, the mRNA levels of Btaf1, Phka1, Nav1, Bdnf, Magt1, and Grin1 were confirmed by qRT‐PCR." (PMID 35770064, 2022).
hemangioma (2 papers, 2019 to 2022). A benign vascular lesion characterized by the formation of capillary-sized or cavernous vascular channels. "Endothelial differentiation markers, CD31 and CDH5 and hemangioma endothelial markers NOTCH1, PLXND1 and VEGFR1 under each treatment condition in four biological replicates, determined by qPCR, were standardized as described." (PMID 31358114, 2019). "(C) VEGF-B treatment of HemSC from four different infantile hemangiomas resulted in increased CDH5 (an endothelial cell marker), SOX18 and ADBR2 (β2 adrenergic receptor) mRNA." (PMID 31358114, 2019).
malignant glioma (2 papers, 2013 to 2022). A grade III or grade IV glioma arising from the central nervous system. "CDH5 is an endothelial cell marker whose overexpression in malignant gliomas is shown to portray an adverse prognosis, as it promotes the trans-differentiation of GSCs into endothelial-like cells to induce angiogenesis." (PMID 35456993, 2022).
meningitis (2 papers, 2020 to 2022). A disorder characterized by acute inflammation of the meninges of the brain and/or spinal cord. "The changes in Cdh5 and Cldn5 expression observed in the present study are consistent with the previous findings reported in a Staphylococcus aureus and group B Streptococcus model of meningitis." (PMID 32509459, 2020).
mesothelioma (2 papers, 2017 to 2020). A usually malignant and aggressive neoplasm of the mesothelium which is often associated with exposure to asbestos. "Mutations and copy number changes in CDH5 have been previously reported in mesotheliomas but are uncommon events and were not present in any of our reference mesothelioma datasets." (PMID 32545767, 2020).
osteosarcoma (2 papers, 2024 to 2025). A usually aggressive malignant bone-forming mesenchymal neoplasm, predominantly affecting adolescents and young adults. "The vascularendothelial cell population in the osteosarcoma lesion tissues exhibiteda PECAM1­(+), CDH5­(+) phenotype, whereas the macrophage populationwas predominantly of the M2 type, expressing CD163­(+) and MRC1­(+),consistent with the characteristics of the tumor immune microenvironment." (PMID 40834268, 2025).
periapical granuloma (2 papers, 2022). Chronic nonsuppurative inflammation of periapical tissue resulting from irritation following pulp disease or endodontic treatment. "CDH5 is closely related to OS and periapical granuloma, and its pertinent pathways include signal transduction, blood-brain barrier, and immune cell migration." (PMID 35075370, 2022).
pterygium (2 papers, 2021 to 2022). A wedge-shaped fibrovascular lesion arising from the bulbar conjunctiva and extending to the cornea. "Moreover, CDH5 and CDH6, two important epithelial cell adhesion factors, were highly expressed in pterygium tissues investigated in this study." (PMID 33790949, 2021).
Ureteral obstruction (2 papers, 2021 to 2025). Obstruction of the flow of urine through the ureter. "In the context of kidney fibrosis in the ureteral obstruction mouse model, 10% of fibroblasts appeared to be of endothelial origin using the Cdh5-Cre; YFPf/f line for lineage tracing." (PMID 34445337, 2021).
Anxiety (1 paper, 2020). Intense feelings of nervousness, tension, or panic often arise in response to interpersonal stresses. "Conversely, multiple studies have a found a decreased expression of CDH5 in the PFC of SCZ individuals, while genetic knockdown of CDH5 in mouse PFC led to BBB disruption and changes in behavior including deficits in learning, memory, sensorimotor gating, and anxiety-like behavior." (PMID 33061891, 2020).
aortic disorder (1 paper, 2023). Pathology involving the thoracic, thoracoabdominal, or abdominal aorta (including aneurysms). "Cadherin-5 (vascular endothelial-cadherin) is reported to play important roles in several types of aortic disorders." (PMID 36672669, 2023).
arteriosclerosis (1 paper, 2021). A vascular disorder characterized by thickening and hardening of the walls of the arteries. "Cdh5‐CreERT2 × Rosa26‐tdTomato mice with or without four pulses of tamoxifen administration were used in the isografting model for inducible and irreversible labelling and tracing of ECs (CADH5+ cells) and their progeny in aortic graft arteriosclerosis." (PMID 33125708, 2021).
Behçet disease (1 paper, 2023). "Previous studies have reported increased circulating cadherin-5 levels in patients with Behçet disease and IgAV." (PMID 37238213, 2023).
Cantú syndrome (1 paper, 2024). "To investigate changes in CCh-induced endothelial cell Ca2+ signaling associated with Cantú syndrome, we crossed Cdh5-GCaMP8 and Kir6.1wt/VM mice." (PMID 39088268, 2024).
glomerular disease (1 paper, 2024). "In contrast, deletion of Col4a3 in endothelial cells (Cdh5-Crepos; Col4a3L/L) did not result in glomerular disease, with no impact on survival, renal function, and kidney histopathology." (PMID 38561223, 2024).
gout (1 paper, 2025). A condition characterized by painful swelling of the joints, which is caused by deposition of urate crystals. "Elevated CDH5 levels in both AGA and CGA sera point to vascular endothelial injury as an early and sustained event in gout progression, while decreased PPP1R15A implies compromised cellular stress responses." (PMID 41511324, 2025).
H1N1 influenza (1 paper, 2023). "Cdh5-CreERT2; ROSA26LSL-tdTomato (Atf3EC-WT) and Cdh5-CreERT2; ROSA26LSL-tdTomato; Atf3lox/lox (Atf3EC-KO) adult mice (5–15 weeks old) received 200 mg/kg tamoxifen by oral gavage 2 weeks before H1N1 influenza injury or PBS administration (control)." (PMID 37233732, 2023). "Cdh5-CreERT2; ROSA26LSL-tdTomato (Atf3EC-WT, n=4) and Cdh5-CreERT2; ROSA26LSL-tdTomato; Atf3lox/lox (Atf3EC-KO, n=3) adult mice received 200 mg/kg tamoxifen by oral gavage 2 weeks before H1N1 influenza injury." (PMID 37233732, 2023).
Hepatic steatosis (1 paper, 2024). Steatosis is a term used to denote lipid accumulation within hepatocytes. "More specifically, iECSema3a mice and Cdh5-CreERT2 controls (abbreviated as iECwt) were fed an HFD for 10 weeks to induce hepatic steatosis, followed by injections with tamoxifen to efficiently delete the Sema3a allele." (PMID 39196233, 2024).
hyperandrogenism (1 paper, 2025). Excessive secretion of androgens from the adrenal glands or gonads. "The proteins IGFBP5, LAMP2, and CDH5 may contribute to the mechanisms underlying the adverse effects of hyperandrogenism on oocyte quality in PCOS patients." (PMID 40444232, 2025). "In summary, IGFBP5, LAMP2, and CDH5 may be involved in the process by which hyperandrogenism affects oocyte quality in PCOS patients." (PMID 40444232, 2025).
intracranial hemorrhage (1 paper, 2017). Bleeding within the SKULL, including hemorrhages in the brain and the three membranes of MENINGES. "Knockdown or mutation of miR-132 caused severe intracranial hemorrhage and disruption of brain vascular integrity in zebrafish larvae with reduced expression of the adherens junction protein vascular endothelial cadherin (VE-cadherin, also known as Cdh5) and its intracellular partner β-catenin." (PMID 28429770, 2017). "Similar to the effects of miR-132 knockdown, Cdh5 morphants also displayed increased intracranial hemorrhage (see also ref.27) and DAPI leakage (P < 0.001)." (PMID 28429770, 2017). "In comparison with tdT expression in ECs (“Flk1:tdT”), miR-132-S expression in ECs resulted in severe intracranial hemorrhage (P < 0.01) and reduction of Cdh5 expression (P < 0.01)." (PMID 28429770, 2017). "Furthermore, EC-specific overexpression of Eef2k (“Flk1:tdT-P2A-Eef2k”) also caused intracranial hemorrhage (P < 0.01), DAPI leakage (P < 0.001), and reduction of Cdh5 expression (P < 0.01)." (PMID 28429770, 2017). "In comparison with control larvae, in which neurons expressed tdT (“HuC:tdT”), larvae with neurons expressing miR-132-S exhibited severe intracranial hemorrhage (P < 0.01) and increased DAPI leakage (P < 0.05) and reduced Cdh5 expression (P < 0.05)." (PMID 28429770, 2017). "Moreover, knockdown of eef2k alleviated the intracranial hemorrhage (P < 0.01), DAPI leakage (P < 0.05) and reduction of Cdh5 expression (P < 0.05) in miR-132 morphants." (PMID 28429770, 2017).
Kawasaki disease (1 paper, 2022). A rare inflammatory disease characterized by an acute febrile, systemic, self-limiting, medium-vessel vasculitis primarily affecting children. "Genotype frequency distributions of CDH5 rs7404339 polymorphism in Kawasaki disease (KD) cases and controls." (PMID 35571208, 2022). "Stratification analysis of CDH5 rs7404339 polymorphism in Kawasaki disease (KD) cases and controls." (PMID 35571208, 2022).
lymphangiectasia (1 paper, 2022). "To investigate the endothelial cell–specific role of oncogenic KRASG12D mutations in lymphangiectasia, we generated KrasG12Dfl/+; Cdh5CreERT2 mice, in which tamoxifen administration activates the gain-of-function KrasG12D allele specifically in Cdh5+ endothelial cells." (PMID 36073544, 2022).
malignant mesothelioma (1 paper, 2020). A malignant neoplasm of the pleura or peritoneum, arising from mesothelial cells. "Using whole exome sequencing of five WDPMs of the peritoneum, we have identified distinct mutations in EHD1, ATM, FBXO10, SH2D2A, CDH5, MAGED1, and TP73 shared by WDPM cases but not reported in malignant mesotheliomas." (PMID 32545767, 2020).